CD4 (CD4 molecule)
Diseases named in the same sentence as CD4 in open-access papers (continued):
Sharing a sentence is not in itself a finding about the gene and the disease.
Immunodeficiency (continued). "In the present study, we showed that T-peptide had the ability to regulate immune dysfunction of CD4+ T lymphocytes in vitro." (PMID 26577833, 2015). "The majority of patients presented with severe immunodeficiency (CD4+ T-cell counts ≤200 cells/mm3) or AIDS-related diseases at cART initiation." (PMID 24789106, 2014). "At the time of ART initiation, patients had advanced immunodeficiency with the median baseline CD4+ T - cell counts of 152 cells/mm3 (IQR = 82 - 203 cells/mm3)." (PMID 25164855, 2014). "In our study, immunodeficiency (most recent CD4 count <350 cells/mm3) was identified as the main determinant of the presence of CIN+ in HIV-infected women and this association remained although with a lower strength among those on ART." (PMID 24595037, 2014). "These somewhat discordant findings raise questions on the respective role of cumulative time spent on immunodeficiency as well as the CD4 nadir reached before ART is initiated." (PMID 24595037, 2014). "The lymphocytopenia, low CD4+ count, and failed response to pneumococcal vaccination that presented in our patient are consistent with immunodeficiency." (PMID 25528459, 2014). "This was probably largely the result of severe overall immunodeficiency in the study population, as reflected by the low mean CD4+ cell counts (278 cells/μL) and very high hospitalization rate (32.9%) and occurrence of cryptosporidiosis (26.9%)." (PMID 24743521, 2014). "Previous studies have reported an association between the presence of cytological abnormalities and a severe immunodeficiency (most recent CD4 count measure <200 cells/mm3) among HIV-positive women in sub-Saharan Africa." (PMID 24595037, 2014). "To identify changes that accompany immune-dysfunction during human aging, we analyzed gene expression patterns in CD4+ T cells from 31 donors ranging in age from 25-81 years." (PMID 25553802, 2014). "In conclusion, we found that patients with CLL in Sichuan province display a CD4+ cell-mediated immune disorder." (PMID 25225540, 2014). "This, to our knowledge, is the first successful molecular classification of SAR using CD4+ T-cells, and highlights the potential of genome-wide epigenetic technologies in the stratification of immune disease." (PMID 24391521, 2014). "Despite normalization of total CD4 counts, ongoing immune dysfunction is noted amongst those on antiretroviral therapy (ART)." (PMID 25393989, 2014). "The observed higher sensitivity of Xpert MTB/RIF for sputum-based TB diagnosis among those with the lowest CD4 cell counts appears to run contrary to the widely-held dogma that sputum mycobacterial load declines linearly with advancing immunodeficiency." (PMID 24168211, 2013). "HIV disease progression and immunodeficiency (indicated by CD4 decline) are largely prevented by early initiation of treatment and sustaining an undetectable VL." (PMID 24348722, 2013). "The proportion of patients with positive test results among those with severe immunodeficiency (CD4 count <100 cells/μl) was higher with IGRAs as compared to the TST (26% vs. 13%, p = 0.12) but the differences were not statistically significant." (PMID 24176032, 2013). "We found an early initial increase in the frequency of CMV-Sp-CD4 (as % of CD4 T cells) at week 4, especially in those with advanced immunodeficiency with CDC category C or lower CMV-Sp-CD4 T cells at baseline." (PMID 24130889, 2013). "We confirm an inverse relation between 25(OH)D levels and immunodeficiency, with the proportion of persons with a CD4 count below 100/mm3 being higher in persons with 25(OH)D<10 ng/mL." (PMID 24058636, 2013). "The difference in the proportion of PLWH testing TST-positive when using the two different cut-off sizes was similar across the range of CD4+ cell count strata suggesting use of this cut-off across the spectrum of immunodeficiency." (PMID 23834892, 2013).
Immunodeficiency (continued). "In a sub-analysis, only patients with baseline immunodeficiency (CD4 < 100 cells/mm3) showed a significant improvement in physical activity (p = 0.028)." (PMID 23919622, 2013). "Immunodeficiency was advanced with a median blood CD4 lymphocyte count of 109 cells/μL (IQR, 53–168)." (PMID 23472118, 2013). "Median CD4%/count increased (p<0.001) and the proportion with severe immunodeficiency dropped from 98 to 82% and with WHO Stage III/IV disease from 81 to 63%." (PMID 24363808, 2013). "We also tested if the degree of immunodeficiency as measured by the nadir CD4 T cell count (defined as the lowest CD4 T cell count ever measured in a patient) would have an impact on the association between host population and M. tuberculosis lineage." (PMID 23505379, 2013). "Our patient has immuno-clinical antiretroviral therapy failure (CD4 count 6 cells/mm3) corresponding to severe immunodeficiency." (PMID 24304699, 2013). "This indicated that advanced pre-treatment immunodeficiency is the most important factor for diminished restoration of CD4 cell counts after HAART." (PMID 23842109, 2013). "HIV-1 replicates in activated CD4+ T cells, monocytes or dendritic cells and leads to immunodeficiency characterised by progressive CD4+ T-cell depletion." (PMID 23147374, 2013). "Trial data also demonstrated that mortality was reduced in those with the most severe immunodeficiency (CD4 cell counts <50 cells/μl) if they stated ART within the first 2 weeks of TB treatment." (PMID 24295487, 2013). "In the settings of immunodeficiency secondary to solid organ or stem cell transplant, the presence of CMV-Sp-CD8 T cells and CMV-Sp-CD4 T cells are associated with lower levels of CMV viraemia and reduced risk of symptomatic CMV disease." (PMID 24130889, 2013). "This proportion was similar across the range of CD4+ cell strata, supporting the current standardization of this cut-off at all levels of immunodeficiency." (PMID 23834892, 2013). "Though a large number of children had severe immunodeficiency at base line, the mean increment of CD4 count was remarkable until 12 months after initiation of ART (P < 0.0001)." (PMID 22916836, 2012). "Given advanced immunodeficiency (CD4<200 cells/mm3) at ART initiation in all included women, it is not surprising that we observed somewhat lower pregnancy rates than the 9.0/100 women-years on ART recently reported from the MTCT-Plus initiative." (PMID 22615543, 2012). "Overall, patients had advanced immunodeficiency at enrolment with a median baseline CD4 cell count of 98 cells/μL (IQR 48–155)." (PMID 22479548, 2012). "There was a poor correlation between clinical staging and immunological status: of children in clinical stage 3 or 4, 47% also had severe immunodeficiency according to CD4 cell percentage-for-age." (PMID 22400106, 2012). "The effect of HIV-related immunodeficiency in the coinfected patients was strong (an increase of 3.5% in the FIB-4 score for every 100 CD4 cells/μL decrease)." (PMID 23056462, 2012). "Apoptosis of uninfected bystander cells is a key element of HIV pathogenesis and believed to be the driving force behind the selective depletion of CD4+ T cells leading to immunodeficiency." (PMID 23202514, 2012). "Immunodeficiency was advanced in both adolescents and young adults, as reflected by baseline CD4 cell counts." (PMID 22273267, 2012). "Finally, to explain an association between HIV related immunodeficiency and HBsAg levels in more detail we have analyzed the effect of cART induced immune restoration, in this case a difference between current CD4 T-cell count and nadir CD4 T-cell count (ΔCD4)." (PMID 22905219, 2012). "In conclusion, our data showed that a genetic variant of APOBEC3G genotypes, H186 in GG, was significantly associated with decline in CD4% and the CD4 count over time in Thai and Cambodian ART-naïve HIV-infected children with moderate immune deficiency." (PMID 23181827, 2012).
Immunodeficiency (continued). "The potential usefulness of the Determine TB-LAM assay was evident in patients with advanced immunodeficiency when data were stratified by CD4 cell count." (PMID 22015305, 2012). "In this study, we demonstrated the association of a genetic variant of APOBEC3G genotypes, H186 in GG, with the decline in CD4% and the CD4 count over time in Thai and Cambodian ART-naïve HIV-infected children with moderate immune deficiency." (PMID 23181827, 2012). "As is common in our country, HIV was diagnosed late, usually with symptoms of immunodeficiency and low baseline lymphocyte CD4 count." (PMID 22359615, 2012). "HIV infections cause a progressive depletion of a select group of immune cells namely the CD4+ T helper cells leading to immunodeficiency." (PMID 23202514, 2012). "The increased levels of IL-15 found in several CD4+ T cell-driven (auto-) immune diseases prompted us to examine how IL-15 influences murine CD4+ T cell responses to low dose TCR-stimulation in vitro." (PMID 23028916, 2012). "Increased TGF-β and Foxp3 at sites of inflammation was associated with elevated CD4+CD25+Foxp3+ Treg populations, which can down-regulate the progression of experimental immune disorders." (PMID 22873180, 2012). "Our results highlight the potential contribution of altered sphingolipid composition to immune dysfunction in aged CD4+ T cells." (PMID 23110086, 2012). "In MM, several studies have previously shown that CD4 regulatory T (Treg) cells hamper effector T cell functions and enhance immune dysfunction." (PMID 23152910, 2012). "The three patients described here showed an advanced HIV-1 disease with an unexpected increase of LFTs occurred in the presence of a severe immunodeficiency (CD4+ T cells < 200/cu.mm)." (PMID 21362160, 2011). "In preliminary studies, FIV-PCenv viremia kinetics displayed a lag period during the first month of infection, as well as a delay in classic indicators of immunodeficiency as reflected in drops in CD4+ T cell and neutrophil counts compared to parental viruses." (PMID 21887365, 2011). "Immunodeficiency assessed by both nadir and current CD4 cell count has been shown to predict the occurrence of NADM in various studies." (PMID 21443771, 2011). "Like HIV, MoMuLV ts-1 infects CD4 cells, with subsequent CD4 depletion and a resulting immunodeficiency." (PMID 22312355, 2011). "Patients typically had advanced immunodeficiency (median CD4 cell count, 171 cells/μl), and 26.5% of patients had previously had TB." (PMID 21818180, 2011). "Patients who presented better immunity (CD4 ≥ 200) were more than two and a half times more likely to test positive that those with higher levels of immunodeficiency (CD4 < 200)." (PMID 21892936, 2011). "Human immunodeficiency virus (HIV) infection is characterized by a loss of CD4+ T-cells and a progressive loss in cytotoxic T-cell lymphocyte (CTL) function resulting in immunodeficiency." (PMID 21920046, 2011). "The mechanism by which HIV infection leads to a selective depletion of CD4 cells leading to immunodeficiency remains highly debated." (PMID 21255440, 2011). "These include CD4 cell targeting, secondary infections, neurodegenerative diseases, macrophage and CD4 cell infection, immunodeficiency, neurotropism, CD4 cell depletion, wasting, lymphomas, and perinatal transmission." (PMID 22312355, 2011). "Majority (73%) of the 208 patients in the study group had a CD4 count of <200/mm3 indicating progressive immunodeficiency." (PMID 21814542, 2011). "We report three cases of HIV-1 infected patients with advanced immunodeficiency (CD4+ T lymphocytes less than 200/cu.mm)." (PMID 21362160, 2011). "The majority of patients had severe immunodeficiency (57.2%), as reflected in the low median CD4 percentage of 15 (IQR 9–22)." (PMID 21695087, 2011).
Immunodeficiency (continued). "In our study, the nadir CD4 T-cell count best reflects the level of immunodeficiency reached by the women since at cohort enrollment 27% of the women were already receiving HAART for more than 2 months." (PMID 21479179, 2011). "Our findings suggest that this rural Ugandan population with chronic untreated subtype A HIV-1 is similar to other HIV-infected populations, where CD4+ T cell decline, increased viral load and subsequent immune dysfunction have been observed." (PMID 21886768, 2011). "Our finding that CD4+ T-lymphocyte percentages were relatively stable through 5 years of age in Malawian children contrasts with the WHO threshold values for immunodeficiency, which fall with age in a stepwise manner from 0 to 5 years." (PMID 19944455, 2010). "Our lower rate should be explained by the profound immunodeficiency of our patients at the time of treatment initiation (median CD4 count of 135 cells/mm3)." (PMID 20193053, 2010). "Immunodeficiency was advanced with a median blood CD4 lymphocyte count of 124 cells/μL (IQR, 63-192)." (PMID 21078148, 2010). "The CD4 ranges would also help in the management of immunodeficiencies other than HIV and in the assessment of immune reconstitution." (PMID 21245613, 2010). "The proportion of children with severe immunodeficiency at baseline was, however, higher in the rural group (p = 0.043), and remained higher up until the 12-month CD4 cell measurement (p = 0.20)." (PMID 21108804, 2010). "Uninfected CD4 T cells undergo X4 Env-mediated autophagy, leading to their apoptosis, a mechanism now recognized as central to immunodeficiency." (PMID 19492063, 2009). "Most patients who reached the ART centre would have a CD4 test done, hence—with half the CD4 information missing—our results regarding ART initiation across different levels of immune deficiency should be interpreted with caution." (PMID 19936067, 2009). "Both HIV-1 and HIV-2 infections are associated with a persistent generalized immune-activation, which is considered a main determinant of the immunodeficiency and that inversely correlates with CD4 T cell counts." (PMID 19936055, 2009). "Because CXCR4 and CCR5 are found on different CD4+ T cells, X4 depletes a second set of critical immune cells, accelerating immunodeficiency and death." (PMID 19680436, 2009). "Overall, the NNS was lower the more advanced the degree of immunodeficiency as manifested by CD4 count and WHO clinical status." (PMID 19775470, 2009). "CD4% was available for 194 children with 41% of them showing severe immunodeficiency (CD4 <15%) at the time of initial presentation." (PMID 20041007, 2009). "We mainly observed a marked decrease in the percentage of children with the most severe immunodeficiency (<15% CD4)." (PMID 19681795, 2009). "Additionally, the subjects with rapid CSF-compartmentalized variant decay had significantly higher CD4 counts than subjects with slow compartmentalized variant decay, indicating that subjects with slow decay of CSF-compartmentalized virus have increased immunodeficiency." (PMID 19390619, 2009). "This causes the uninfected memory CD4+ T cell population to increase during anti-CCR5 therapy, yielding a drop in an/am and hindering a potential switch to X4 as well as immunodeficiency (small kM4 regime)." (PMID 19680436, 2009). "Surprisingly, IRIS was uncommon in this study (7%) although subjects had very advanced immunodeficiency, were receiving ART early in their OI treatment course, and had good increases in CD4 counts - all conditions that have been associated with IRIS." (PMID 19440326, 2009). "As CD4+ count is a reflection of the state of the immune system, it reasonable to assume that the immune dysfunction noted at lower CD4+ levels is responsible for the increased detection of high-risk HPV in these women." (PMID 19208213, 2009).
Immunodeficiency (continued). "Nevertheless, evidence linking immunodeficiency in ALS syndromes include the loss of CD8+ T cells in ALS patients and the loss of CD4+ T cells in HIV-infected patients that displayed ALS-like syndromes." (PMID 18648532, 2008). "The determination of CD4 count has become a standard measure of immunodeficiency in adults infected with HIV in resource rich areas where the burden of the pandemic is low." (PMID 19102769, 2008). "It is well known that HIV-1 viremia induces a CD4+ T cell depletion that leads to immunodeficiency and correlates with disease progression." (PMID 18617991, 2008). "With CD4 playing a key role in immunity, therapeutic research of CD4 mAbs was initially focused on inflammatory and (auto) immune diseases." (PMID 18702090, 2008). "Our data extend this observation to patients with advanced immunodeficiency (median CD4 cell count = 114 cells/μl)." (PMID 17725839, 2007). "CD4 cell counts showed that immunodeficiency was advanced in most patients; 48% had a history of completed treatment for TB within the preceding 3 years consistent with previous findings." (PMID 17725839, 2007). "We observed a high risk of low antibody levels for all EPI vaccines, except OPV types 1 and 2, in HIV-infected children with severe immunodeficiency (CD4+ T cells <25%)." (PMID 18060056, 2007). "Several mechanisms have been postulated to explain the role of steroids in promoting the development of P. jiroveci including CD4+ lymphocyte depletion and immune dysfunction." (PMID 15488151, 2004). "In current clinical practice, the CD4+ T lymphocyte count remains a cornerstone metric for assessing the degree of immunodeficiency, guiding disease staging, and informing management decisions in people living with HIV, with its prognostic value being well-established." (PMID 41601726, 2026). "Of 387 with CD4 data, 149 (38.5%; 95% CI 33.6-43.6) had severe immunodeficiency (<200 cells/μL)." (PMID 41994513, 2026). "Although CD4+ T cell depletion is the main driver of HIV-1–induced immunodeficiency, the virus also exerts a significant and often underestimated impact by disrupting the function of STAT family members, thereby exacerbating immune imbalance and accelerating disease progression." (PMID 41009690, 2025). "However the recovery of circulating CD4 T cells does not parallel the situation of tissues (such as GALT), in which the recovery of CD4 T cells is minimal and partial immunodeficiency is permanent." (PMID 41373539, 2025). "This selective effect reflects targeted exhaustion and depletion rather than global CD4+ T cell suppression, thus minimizing the risk of broad immunodeficiency." (PMID 41402667, 2025). "Most participants did not have an immune deficiency as defined by the WHO pediatric antiretroviral treatment guidelines (median CD4 count of 603 cells/μl)." (PMID 39879199, 2025). "Reports suggest that the CD4:CD8 ratio may demonstrate immune dysfunction in patients with well-controlled HIV infection better than the CD4 cell count alone." (PMID 40003876, 2025). "In HIV-positive individuals, immune dysfunction—characterized by reduced CD4+ T-cells and immune activation—could permit persistent HHV infections, even in the absence of overt periodontal disease." (PMID 40150657, 2025). "Pregnant women with HIV have high levels of inflammation and residual immune dysfunction (decrease in CD4+ T cells); even with the use of effective antiretroviral therapies (ARTs), the culmination of both disrupts fetal immune homeostasis and alters long-term immune cell function in these children." (PMID 40661959, 2025). "In conclusion, our results show that PLWH on successful treatment with a CD4/CD8 ratio below 0.76 displayed higher levels of immunosenescence markers in T-cells, while those with a CD4/CD8 ratio below 0.4 showed the strongest degree of immune dysfunction, including a decrease in NK-cells." (PMID 40303366, 2025).